FNBP1L (formin binding protein 1 like)
Description:
Required to coordinate membrane tubulation with reorganization of the actin cytoskeleton during endocytosis. May bind to lipids such as phosphatidylinositol 4,5-bisphosphate and phosphatidylserine and promote membrane invagination and the formation of tubules. Also promotes CDC42-induced actin polymerization by activating the WASL/N-WASP-WASPIP/WIP complex, the predominant form of WASL/N-WASP in cells. Actin polymerization may promote the fission of membrane tubules to form endocytic vesicles. Essential for autophagy of intracellular bacterial pathogens.
Synonyms: C1orf39; TOCA1; FLJ20275
Tractability: Antibody: UniProt places it where antibodies can reach, with medium confidence; its Gene Ontology location is reachable by antibodies, with medium confidence. PROTAC: ubiquitination databases record sites on it; its protein half-life has been measured.
Gene: Protein-coding gene on chromosome 1 (93,448,055 to 93,554,661, forward strand). Ensembl gene ENSG00000137942.
Subcellular location: Cytoplasm; Cytoplasm, cytoskeleton; Cytoplasm, cell cortex; Cytoplasmic vesicle; Cell membrane
Subcellular location (Human Protein Atlas): Cytosol; Vesicles
Pathways (Reactome):
Signal Transduction: CDC42 GTPase cycle; RHOJ GTPase cycle
Vesicle-mediated transport: Clathrin-mediated endocytosis
Gene Ontology:
Molecular function: cadherin binding; GTPase binding; protein binding
Biological process: cilium assembly; clathrin-dependent endocytosis; membrane invagination; plasma membrane tubulation; positive regulation of filopodium assembly; vesicle budding from membrane; vesicle organization; vesicle transport along actin filament; signal transduction
Cellular component: cytoplasm; cytoplasmic vesicle; cytosol; cell cortex; cytoskeleton; plasma membrane
Genetic constraint (gnomAD): Loss-of-function variants: 24 observed, 46.95 expected, observed/expected ratio (o/e) 0.51, 90% interval 0.37 to 0.72. The upper end of that interval is the gene's LOEUF score, 0.72, which puts it in group 2 of 6, group 1 being the genes least tolerant of losing a copy. Missense variants: 452 observed, 518.9 expected, observed/expected ratio (o/e) 0.87, 90% interval 0.81 to 0.94. Synonymous variants: 184 observed, 171.97 expected, observed/expected ratio (o/e) 1.07, 90% interval 0.95 to 1.21.
Homologues: Orthologues: dog FNBP1L (99% identical), rabbit FNBP1L (99% identical), macaque FNBP1L (99% identical), chimpanzee FNBP1L (98% identical), pig FNBP1L (98% identical), rat Fnbp1l (98% identical), guinea pig FNBP1L (96% identical), mouse Fnbp1l (88% identical), tropical clawed frog fnbp1l (77% identical), zebrafish fnbp1l (69% identical), Drosophila melanogaster Cip4 (36% identical), Caenorhabditis elegans toca-1 (25% identical), and 1 more. Paralogues in human: FNBP1 (57% identical), TRIP10 (52% identical).
Diseases named in the same sentence as FNBP1L in open-access papers:
FNBP1L is named in the same sentence as 16 diseases in open-access papers, as found by Europe PMC text mining. Sharing a sentence is not in itself a finding about the gene and the disease. The quoted sentences say what the papers report.
breast carcinoma (5 papers, 2014 to 2021). "FNBP1L promotes epidermal growth factor-induced cell migration and invasion in epidermal and breast cancer." (PMID 34722771, 2021).
HIV-1 infection (1 paper, 2025). The type species of lentivirus and the etiologic agent of acquired immunodeficiency syndrome (AIDS). "In a selective, shRNA-mediated knockdown screen in primary monocyte-derived dendritic cells (MDDCs) infected with HIV in the presence of SAMHD1-disactivating Vpx containing virus-like particles, three proteins hampering HIV-1 infection were identified: FNBP1L, ARHGAP24, and ATP6V1B1." (PMID 40029073, 2025). "FNBP1L, ARHGAP24, and ATP6V1B1 knockdown repeatedly proved to increase HIV-1 infection in additional donors, confirming screening observations." (PMID 40029073, 2025). "Over a 7-day period in THP1 cells, knockdown of FNBP1L, ARHGAP24, and ATP6V1B1 resulted in sustained enhancement of HIV-1 infection." (PMID 40029073, 2025). "Depletion of FNBP1L, ARHGAP24, and ATP6V1B1 showed increased entry rates upon HIV-1 infection." (PMID 40029073, 2025). "From this group, the actin cytoskeleton regulators FNBP1L and ARHGAP24, along with the vacuolar proton pump ATP6V1B1, were prioritized for further study due to their strong impact and lack of prior association with HIV-1 infection in the literature." (PMID 40029073, 2025). "Our results show that the depletion of FNBP1L, ARHGAP24, and ATP6V1B1 enhances HIV-1 infection in MDDCs, but not in CD4+ T cells." (PMID 40029073, 2025). "Knocking down FNBP1L, ARHGAP24, and ATP6V1B1 in CD4+ T cells did not enhance HIV-1 infection, contrasting sharply with the significant effects observed in MDDCs." (PMID 40029073, 2025).
preeclampsia (1 paper, 2024). Preeclampsia is a hypertensive disorder of pregnancy that is characterized by new-onset hypertension with proteinuria presenting after 20 weeks of gestation, and depending on mild or severe forms may initially present with severe headache, visual disturbances, and hyperreflexia. "In this study, we observed significant differences in the expression levels of FNBP1L, NMUR1, and PP14571 genes in patients with preeclampsia." (PMID 38846957, 2024).
tumor (2 papers, 2014 to 2021). "The median relative expression of FNBP1L was 1.31 in paracancerous tissues and 0.57 in ESCC tissues, which was significantly decreased in tumor tissues (Wilcox test, P = 0.026)." (PMID 34722771, 2021).
FNBP1L also shares sentences with these, for which no sentence is quoted: infection (4 papers); bacterial infection (1); breast tumors (1); cancer (1); colon cancer (1); fibrosarcoma (1); invasive ductal carcinomas (1); mammary adenocarcinoma (1); melanoma (1); metastatic disease (1); neuroblastoma (1); prostate carcinoma (1).